SLX4 (SLX4 structure-specific endonuclease subunit)
Diseases named in the same sentence as SLX4 in open-access papers (continued):
Sharing a sentence is not in itself a finding about the gene and the disease.
ovarian carcinoma (5 papers, 2020 to 2025). A malignant neoplasm originating from the surface ovarian epithelium. "SLX4 is less known than the others, because its pathogenic variants are rare, although one large sequencing study suggested a potential role for ovarian cancer risk." (PMID 39400928, 2025). "In conclusion, these findings suggested that USP28/SOX9 positively regulates the expression of DDR genes (SMARCA4, UIMC1, and SLX4) by binding to their promoters in ovarian cancer cells." (PMID 40240356, 2025). "We observed that olaparib promotes the expression of SMARCA4, UIMC1, and SLX4 in ovarian cancer cells." (PMID 40240356, 2025). "Other candidate genes selected for targeted sequencing validation in cases and controls have shown weak evidence of association with ovarian cancer risk for protein truncating variants in POLK, SLX4 (also known as FANCP), and FBXO10, but further studies are required to confirm this." (PMID 33086730, 2020). "ChIP-Seq analysis revealed that SOX9 binds to the promoters of key DNA damage repair (DDR) genes (SMARCA4, UIMC1, and SLX4), thereby regulating DDR processes in ovarian cancer." (PMID 40240356, 2025). "Our further research showed that USP28/SOX9 modulate the HRR activity of ovarian cancer by regulating SMARCA4, UIMC1, and SLX4 expression." (PMID 40240356, 2025).
viral infection (3 papers, 2014 to 2025). "Overexpression of JAK1, TYK2, MAP2K1, IFNG, TRPM2, and ADCY9 significantly inhibited viral infection, whereas overexpression of SNX27, GATA4, EHMT2, PCBP2, SMARCA4, and SLX4 enhanced viral infection." (PMID 40530850, 2025). "In a model in which SLX4 would play a role in the escape from immune sensing by digesting viral DNA, depletion of SLX4 should reduce viral infection." (PMID 25496524, 2014). "Future work should aim at elucidating whether Vpr provides an advantage to viral infection by activating SLX4." (PMID 25496524, 2014). "However, this is not the case, MUS81 depletion does not mimic a G2 arrest phenotype and MUS81 or SLX4 depletion reduces viral infection, which indicates their positive role for the viral life cycle." (PMID 25496524, 2014).
anaemia (2 papers, 2025). "In addition, we identified patients with genetic variants in five members of the Fanconi Anemia Complex (FANCE, SLX4/FANCP, FANCA, FANCI, and FANCC)." (PMID 40894167, 2025).
hereditary cancer (2 papers, 2020 to 2022). Malignant neoplasms occurring in families at a rate greater than that expected by chance and caused by germline mutations in a specific gene. "A prospective cohort of 1021 unrelated cancer cases with clinical suspicion of hereditary cancer was screened for mutations in the following 14 FA genes: FANCA, FANCB, FANCC, FANCD2, FANCE, FANCF, FANCG/XRCC9, FANCI, FANCL/PHF9, FANCM, FANCP/SLX4, FANCQ/ERCC4, FANCR/RAD51 and FANCU/XRCC2." (PMID 32235514, 2020).
HIV-1 infection (2 papers, 2014 to 2024). The type species of lentivirus and the etiologic agent of acquired immunodeficiency syndrome (AIDS). "If SLX4 helps HIV-1 to evade the immune response, then loss of SLX4 should impede HIV-1 infection." (PMID 39205287, 2024). "This expected decrease in HIV-1 infection was observed in cells collected from FANCP patients wherein SLX4 is absent." (PMID 39205287, 2024). "Of note, the decrease in HIV-1 infection under SLX4 depletion was seen in patient samples but not in HeLa cells depleted for SLX4 or MUS81." (PMID 25496524, 2014).
lung carcinoma (2 papers, 2021 to 2023). "Three novel gene–cancer associations were found in this study, namely, PDE11A and PALB2 with lung cancer and SLX4 with liver cancer." (PMID 37610374, 2023).
pancreatic cancer (2 papers, 2022 to 2023). "One patient that also had FH(+), with only one affected relative (third-degree with pancreatic cancer), presented BC as only tumor (diagnosed at 25 years of age), and carried a LPV in SLX4 gene (c.4881del, p.Thr1628fs)." (PMID 36329109, 2022).
prostate carcinoma (2 papers, 2023). A carcinoma that arises from epithelial cells of the prostate gland. "As supportive evidence, SLX4 PGV carriers among high‐grade serous ovarian cancer patients have an odd ratio of 4.07,30 and the SLX4 p.A938Tfs*7 germline variant has been previously identified in prostate cancer." (PMID 37610374, 2023).
Sepsis (2 papers, 2020 to 2024). Sepsis is defined as life-threatening organ dysfunction caused by a dysregulated host response to infection. "SERPINA1, AZU1, MPO and SLX4 genes stand out for their correlation with inflammation and severity and have potential as biomarkers for diagnosing sepsis and predicting poor prognosis." (PMID 39926115, 2024). "Based on their high differential methylation levels and their role in the immune functions identified, four genes (SERPINA1, AZU1, MPO and SLX4) were selected for further validation, supported by available evidence of their biological roles in sepsis." (PMID 39926115, 2024). "Notably, SLX4 hypomethylation showed the highest predictive value for poor prognosis (AUC 0.821), while SERPINA1 hypomethylation exhibited strong diagnostic potential for sepsis (AUC 0.858)." (PMID 39926115, 2024). "Overall, these findings underscore the potential of DNA methylation as biomarkers in sepsis, particularly for AZU1, MPO, SERPINA1, and SLX4, which show strong correlations with clinical indicators of severity and inflammation." (PMID 39926115, 2024).
serous ovarian cancer (2 papers, 2021 to 2023). "The ORs associated for high-grade serous ovarian cancer were 3.01 for PALB2 (95% CI 1.59 to 5.68; p=0.00068), 1.99 for POLK (95% CI 1.15 to 3.43; p=0.014) and 4.07 for SLX4 (95% CI 1.34 to 12.4; p=0.013)." (PMID 32546565, 2021).
B-cell chronic lymphocytic leukemia (1 paper, 2020). "Overexpression of the SLX4 gene has been observed in the B-cell chronic lymphocytic leukemia (BCLL)." (PMID 33195511, 2020).
Bloom syndrome (1 paper, 2012). Bloom syndrome (BSyn) is a rare chromosomal breakage syndrome characterized by a marked genetic instability associated with pre- and postnatal growth retardation, facial sun-sensitive telangiectatic erythema, increased susceptibility to infections, and predisposition to cancer. "Furthermore, a recent study suggests that MUS81, SLX4 and GEN1 can compensate for lack of the BLM helicase in human cells by resolving HJs in somatic Bloom's syndrome cells." (PMID 22927825, 2012).
bowel cancer (1 paper, 2021). "While the germline alterations in certain susceptibility genes were also detected in the bowel cancer samples including FANCD2, CDH1, FLCN, MEN1, SDHB, and SLX4, which have been rarely reported in the Chinese population." (PMID 35154239, 2021).
endometrial cancer (1 paper, 2025). Primary or metastatic malignant neoplasm involving the endometrium (mucous membrane that lines the endometrial cavity).
gastric cancer (1 paper, 2021). A primary or metastatic malignant neoplasm involving the stomach. "SLX4 is known as the most frequently mutated gene in Asian gastric cancer patients." (PMID 34257587, 2021).
Hypertension (1 paper, 2026). The presence of chronic increased pressure in the systemic arterial system. "Notably, 3 variants in SLX4 were significantly more common in Black individuals and associated with both longer telomere length and hypertension risk." (PMID 41718953, 2026).
leukemia (1 paper, 2015). A malignant (clonal) hematologic disorder, involving hematopoietic stem cells and characterized by the presence of primitive or atypical myeloid or lymphoid cells in the bone marrow and the blood. "Taken together, these results suggest that concomitant inheritance of rare variants in FANCA, FANCP/SLX4 and GEN1 on the specific genetic background of this familial case, could lead to increased genomic instability, hematopoietic dysfunction, and higher risk of childhood leukemia." (PMID 26201965, 2015).
melanoma (1 paper, 2016). A malignant, usually aggressive tumor composed of atypical, neoplastic melanocytes. "A similar trend was seen in melanoma, within SLX4, POLE, BRCA1, FANCD2, and ERCC6-mutated tumors containing a significantly higher mutational burden than overall melanoma." (PMID 27004405, 2016).
microcephaly (1 paper, 2021). A congenital or acquired developmental disorder in which the circumference of the head is smaller than normal for the person's age and sex. "Several other DNA damage response proteins, which are binding partners of BRCA1 (such as SLX4, TOP3A, RNF168, and MCPH1) are also associated with microcephaly." (PMID 33441416, 2021).
penile carcinoma (1 paper, 2022). "As of today, it is estimated that SLX4 is essential in cancer but SLX4 mutations in penile carcinomas were not described by the time of writing." (PMID 36564761, 2022).
xeroderma pigmentosum group F (1 paper, 2022). Any xeroderma pigmentosum in which the cause of the disease is a mutation in the ERCC4 gene. "Pull-down experiments employing SLX4 SIMs mutants show the capacity of SLX4 to SUMOylate xeroderma pigmentosum group-F (XPF)." (PMID 35328702, 2022).
cancer (37 papers, 2013 to 2026). A tumor composed of atypical neoplastic, often pleomorphic cells that invade other tissues. "Although this brief communication is limited to onlyin silicoanalysis, it identifies certain high frequency SLX4 mutations in human cancers that would warrant furtherin vivostudies." (PMID 38828439, 2024). "Here we present a pan-cancer analysis of SLX4 mutations using data from the Catalogue of Somatic Mutations in Cancers (COSMIC)." (PMID 38828439, 2024). "In the initial work on SLX4, including cell models expressing different variants of SLX4, the sensitivity to cancer is often used as a read-out to evaluate the implications of the studied interactions in different DNA repair pathways." (PMID 36765954, 2023). "Therefore, coding SLX4 mutations are endemic in cancer cells and loss of function of this enzyme is likely to contribute to cellular transformation and immortalization." (PMID 38828439, 2024). "Moreover, individuals with biallelic mutations in SLX4 present with Fanconi anemia (FA), a disease characterized by cancer predisposition and a sensitivity to ICL-inducing agents." (PMID 33596761, 2021). "Additionally, there are some reports of cancer-predisposition or cancer-associated mutations in SLX4." (PMID 34804132, 2021). "Furthermore, factors required for replication fork stability, repair and restart in response to RS, such as the BRCA1 and BRCA2 proteins, SLX4, and FA group members, have all been shown to associated with cancer development when their function is compromised in either human or mouse models." (PMID 28445142, 2017). "This has shown that SLX4 and/or certain protein interactors of SLX4 can modulate the cellular response to cancer treatments." (PMID 36765954, 2023). "One major consequence of Holliday junction resolution by SLX4 and GEN1 is cancer-causing loss of heterozygosity due to mitotic crossing over." (PMID 33750946, 2021). "The importance of SLX4 for genomic stability is highlighted by observations showing that Slx4-/- mice are born at sub-mendelian ratios and are cancer-prone." (PMID 33596761, 2021). "FANCG, PALB2 and SLX4 homozygous deletions are identified in single carcinomas while FANCM homozygous deletions are identified in 2 carcinomas." (PMID 26438152, 2015). "Unlike the primary (BJ) and telomerase-positive (HT1080 and HeLa) cancer cells, the majority of the SLX4 foci in ALT and HeLa1.2.11 cells colocalized with TRF2 and telomeres." (PMID 24012755, 2013). "SLX4 mutations have been reported in many cancers but a pan cancer map of all the mutations has not been undertaken." (PMID 38828439, 2024). "Notably, SLX4 complex activities have also been implicated in telomere processing mechanisms, particularly at hyperextended telomeres like those of ALT+ cancer cells." (PMID 27829156, 2016). "Our analysis shows that although SLX4 is not a driver gene, it is highly mutated in most cancers." (PMID 38828439, 2024). "However, given the function of SLX4 and the fact that SLX4 mutations occur in nearly all cancers it is not unreasonable to conclude that mutations in this gene also contribute to cancer development." (PMID 38828439, 2024). "Thus,Fig.1Cshould be interpreted with this caveat and not that SLX4 mutations are likely to occur in some cancers more than others." (PMID 38828439, 2024). "The aim of this review is to highlight recent work performed on the activity of a class of cancer drugs (PARP inhibitor) in various cell lines, either expressing or not expressing proteins interacting with the DNA repair protein SLX4." (PMID 36765954, 2023).
cancer (continued). "However, the Chi-squared test χ2 revealed, after exclusion of gender-specific cancer diseases, five different genetic mutations that are significantly more common in men than in women: CDKN2A (p = 0.04), CTNNB1 (p = 0.002), KIT (p = 0.0005), SLX4 (p = 0.034), and VHL (p = 0.046)." (PMID 33114048, 2020). "Of those, we highlight four genes related to cancer development and progression (NOTCH2, ERBB2, MST1R, and RAF1) and two DNA repair genes (ERCC1 and SLX4)." (PMID 29868112, 2018). "Interestingly, Metascape for the first time demonstrated a physical interconnection between CALML3 and DNA repair proteins (BRCA2—Breast Cancer Gene 2, BLM—Bloom syndrome protein, SLX4—Structure-Specific Endonuclease Subunit)." (PMID 41465209, 2025). "For the cancer phenotypes, the reverse genetics models were enriched in DNA repair functions (p = 2×10−5, FDR p = 0.03) (POLG/FANCI, SLX4/FANCP, XRCC1, BRCA1, FANCA, CHD1L) while the additive model showed enrichment related to chromatid segregation (p = 4×10−6, FDR p = 0.005) (KIF25, PINX1)." (PMID 24349080, 2013). "A recent report identified all human cancer driver genes but SLX4 was not listed as a driver gene." (PMID 38828439, 2024). "To date, it has not been possible to produce human SLX4-/- cancer cell lines by CRISPR-Cas9 gene editing, suggesting that SLX4 may be essential in human tumor cells." (PMID 33596761, 2021). "As a result, treatment with ICRF-193 could have an even greater effect on cancer cells which have lost key molecules of the NHEJ pathway, such as 53BP1 or DNAPK, or other important DNA repair factors presented in this study, such as SLX4, and the Ercc1-XPF complex." (PMID 38977669, 2024).
tumor (19 papers, 2013 to 2025). "Sequencing of the SLX4 gene in the tumor from the patient with the truncating mutation revealed loss of the mutant allele." (PMID 23840564, 2013). "In addition, germline PTPRT and SLX4 mutations were significantly associated with smaller tumor sizes (both p < 0.05)." (PMID 35205332, 2022). "We also found that IFNGR2, IQCE, TRPM4, and SLX4 could be associated with SNU-16 derived tumor growth in female mice by endogenous E2." (PMID 34257587, 2021). "We sequenced the SLX4 gene in the tumor from this patient and found loss of the mutant allele." (PMID 23840564, 2013). "We do not yet know which of these functions might be important for tumor suppression in the breast tissue so all known functions of SLX4 need to be tested to make prediction whether an identified variant might lead to loss of SLX4 function." (PMID 23840564, 2013). "Together, these findings provide a mechanistic rationale for targeting the CIP2A-TOPBP1 axis, as well as downstream repair pathways involving SLX4 and Polθ, particularly in tumours that exhibit elevated replicative stress." (PMID 41309571, 2025). "This phenomenon is principally attributed to the presence of cCCT2, which inhibits SLX4 condensate-mediated DNA damage repair pathways by regulating small ubiquitin-like modifier conjugation, thereby promoting tumor cell senescence." (PMID 40686389, 2025). "In summary, mouse Slx4 is a tumor suppressor that also functions to preserve hematopoiesis." (PMID 24726326, 2014). "Loss of the mutant SLX4 allele in the tumor might also suggest that its presence may promote tumor progression by removing essential SLX4-dependent functions during the early stages of tumorigenesis." (PMID 23840564, 2013). "If the W823* and E1517* truncating variants are causative mutations and if these truncated SLX4 proteins are expressed, the differential sensitivity to ICL and other agents may indicate that the SLX4 function associated with MUS81 and/or SLX1 is essential for tumor suppression in the breast tissue." (PMID 23840564, 2013). "Another possibility is that SLX4 might be epigenetically silenced in the tumor." (PMID 23840564, 2013). "For example, the structure-specific endonuclease subunit SLX4 (SLX4) gene, which is essential for DNA damage repair, has been shown to influence ADC responsiveness - tumor cells lacking SLX4 expression exhibit resistance to T-DXd." (PMID 41425250, 2025). "However, the established role of FANCA, SLX4, BRCA2, and ATRX in DNA repair pathways is unlikely to be coincidental, especially considering that we identified mutations in other DNA repair pathway genes, including ATR, which was mutated in two tumours in our study." (PMID 39766052, 2024).
infection (1 paper, 2014). The state of being infected such as from the introduction of a foreign agent such as serum, vaccine, antigenic substance or organism. "Once activated, how does SLX4 distinguish “good DNA” that will lead to productive infection, from “bad DNA” that will be destroyed?" (PMID 25496524, 2014). "If SLX4 drives HIV-1 Vpr function in certain cell types such as macrophages, then, one would like to know whether differences of Vpr alleles to activate SLX4 correlate with different capabilities to help macrophage infection." (PMID 25496524, 2014). "It is also puzzling that no RT product is detected in the SLX4 immunoprecipitate a few hours after infection as we could expect from previous studies." (PMID 25496524, 2014).
SLX4 also shares sentences with these, for which no sentence is quoted: bone marrow failure (6 papers); genetic disorder (3); invasive carcinoma (2); acute myeloid leukemia (1); adenocarcinoma (1); alcoholic liver diseases (1); aplastic anemia (1); autosomal recessive disease (1); bladder cancer (1); cervical cancer (1); cervical dysplasia (1); familial colorectal cancer type X (1); Hepatitis B (1); Hereditary breast cancer (1); leishmaniasis (1); liver cancer (1); mesothelioma (1); mucinous neoplasm (1); Rubinstein-Taybi syndrome (1); squamous cell carcinoma (1); squamous cell carcinoma of the tongue (1); uterine cancer (1).